RDM1 (RAD52 motif containing 1)
Diseases named in the same sentence as RDM1 in open-access papers (continued):
Sharing a sentence is not in itself a finding about the gene and the disease.
lung adenocarcinoma (continued). "Finally, as our Oncomine analyses have shown that up-regulation of RDM1 is generally correlated with poor clinical outcomes, we propose that RDM1 can be a potential prognostic marker for lung adenocarcinoma." (PMID 30069034, 2018). "Collectively, RDM1 in lung adenocarcinoma cells negatively regulated apoptosis, further supporting the notion that RDM1 might play an oncogenic role in lung adenocarcinoma cells." (PMID 30069034, 2018). "In this study, we found that RDM1 played an oncogenic role in human lung adenocarcinoma cells." (PMID 30069034, 2018). "Our study reveals the oncogenic function of RDM1 in human lung adenocarcinoma." (PMID 30069034, 2018). "Therefore, in general, high RDM1 levels were correlated with poor clinical outcomes in human lung adenocarcinoma." (PMID 30069034, 2018). "Given that RDM1 was up-regulated in human lung adenocarcinoma, we first investigated whether RDM1 positively regulated cell proliferation." (PMID 30069034, 2018). "Second, knockdown of RDM1 could reduce cell proliferation of lung adenocarcinoma cells, which might be ascribed to the increased apoptosis." (PMID 30069034, 2018). "In this study, we identified RDM1 as an oncogenic target in lung adenocarcinoma." (PMID 30069034, 2018). "Therefore, knockdown of RDM1 inhibited cell growth of lung adenocarcinoma in vivo." (PMID 30069034, 2018). "But the role of RDM1 in human lung adenocarcinoma remains unknown." (PMID 30069034, 2018). "Therefore, RDM1 may be a new target for the treatment of lung adenocarcinoma." (PMID 30069034, 2018).
neuroblastoma (2 papers, 2019 to 2021). Neuroblastoma (NB) is the most common solid, extracranial childhood tumor. "In neuroblastoma, stable knockdown of RDM1 suppresses tumour growth in vivo, and RDM1 promotes cell proliferation through regulating RAS‐Raf‐Mek‐ERK pathway." (PMID 34264012, 2021). "In neuroblastoma, RDM1 is also reported to increase the protein levels of p‐ERK and p‐MEK." (PMID 34264012, 2021).
Cirrhosis (1 paper, 2020). A chronic disorder of the liver in which liver tissue becomes scarred and is partially replaced by regenerative nodules and fibrotic tissue resulting in loss of liver function. "Consistently, Wurmbach dataset of Oncomine website revealed no RDM1 mRNA differences between normal liver, cirrhosis, HCC, and dysplasia samples." (PMID 31670863, 2020).
hemorrhage (1 paper, 2024). Loss of blood from the vascular compartment to the exterior or into nonvascular body space as a result of rupture or severance of the blood vessels. "A SNP located within 100 Kb of the RDM1 gene was associated with interdigital hyperplasia, and another was associated with sole hemorrhage in Holsteins." (PMID 38601075, 2024).
Hepatitis (1 paper, 2021). Inflammation of the liver. "It was also found that there was a more significant risk ratio in hepatitis-free patients with high RDM1 expression than in carriers, suggesting that increased RDM1 expression in hepatitis-free patients was associated with a poor prognosis." (PMID 34435618, 2021).
malaria (1 paper, 2020). Malaria is a serious and sometimes fatal disease caused by a parasite that commonly infects a certain type of mosquito which feeds on humans. "To test whether Malaria. was binding to proteins on the cell surface, we pre-treated IEs with the proteinases trypsin or pronase E to remove the likely targets and then added Malaria. or the random sequence control, RDM1, to the cells." (PMID 32546848, 2020).
osteosarcoma (1 paper, 2021). A usually aggressive malignant bone-forming mesenchymal neoplasm, predominantly affecting adolescents and young adults. "However, the influence of RDM1 on osteosarcoma (OS) remains unclear." (PMID 34264012, 2021). "However, the effect of RDM1 on osteosarcoma (OS) progression remains unclear." (PMID 34264012, 2021).
tumor (14 papers, 2017 to 2026). "Herein, this study indicated that RDM1 caused an increase in cell proliferation in vitro and tumour growth in vivo, as well as the inhibition of cell apoptosis via inducing cell cycle transition from G1 to S stage, and activating MEK/ERK signalling pathway." (PMID 34264012, 2021). "Additionally, the use of AK4 LUAD tumor gene signatures is associated with the oncogenic protein RAD52 motif Containing 1 (RDM1) at the LUAD tumor stage 2–3 and 3–4 interfaces." (PMID 34940617, 2021). "Knockdown of RDM1 can reduce the proliferation of tumor cells, increase cell apoptosis and induce cell cycle arrest." (PMID 34435618, 2021). "In LIHC, the expression of RDM1 is strongly positively correlated with tumor purity and infiltration of B cells, CD8+ T cells, macrophages and DCs." (PMID 34435618, 2021). "In the present study, the Oncomine and the Tumor Immune Assessment Resource (TIMER) databases were used to verify the expression level of RDM1 messenger RNA (mRNA) in different tumor tissues compared with normal control tissues." (PMID 34435618, 2021). "The data showed that RDM1 expression was significantly correlated with tumor purity in 18 cancer types." (PMID 34435618, 2021). "Our research provides insights to better understand the potential role of RDM1 in tumor immunology and its application as a new immune marker for LIHC." (PMID 34435618, 2021). "Then, the TIMER database was used to assess the RDM1 expression differences in different tumor types." (PMID 34435618, 2021). "In the present study, we used the Oncomine and TIMER databases to reveal significant differences between RDM1 expression in many different tumor types and normal tissues." (PMID 34435618, 2021). "Subsequently, RDM1 silencing not only suppressed cell proliferation in vitro but also inhibited tumour growth in vivo." (PMID 34264012, 2021). "The present study provides a possible mechanism for the expression of RDM1 in regulating tumor immunity by regulating the infiltration of LIHC immune cells." (PMID 34435618, 2021). "Low RDM1 expression was associated with high AFP levels, large tumor size, advanced TNM stage, and poor tumor differentiation." (PMID 31670863, 2020). "In clinical HCC samples, low expression of RDM1 correlates with larger tumor size, poor tumor differentiation, and unfavorable survival." (PMID 31670863, 2020). "Our Oncomine‐based (TCGA database) expression analyses and IHC staining in clinical tumor samples confirmed that RDM1 was high expressed." (PMID 30868057, 2019). "We also report that loss of RDM1 augmented cell apoptosis and induced cell cycle arrest, and that stable knockdown of RDM1 significantly inhibited NB tumor growth in a xenograft mouse model." (PMID 30868057, 2019). "Statistical analyses indicated that up‐regulation of RDM1 was significantly correlated with tumor stage." (PMID 30868057, 2019). "The TCGA database showed that RDM1 expression is significantly correlated with most tumor types." (PMID 34435618, 2021). "In HCC, it was proposed that RDM1 functioned as a tumor suppressor." (PMID 34046411, 2021). "Silencing RDM1 significantly decreased tumour volume and weight, and inhibited tumour growth." (PMID 34264012, 2021). "Also, RDM1 silencing decreased tumour growth in vivo, whereas RDM1 overexpression resulted in the opposite phenotypes." (PMID 34264012, 2021). "Furthermore, RDM1 silencing leads to a significant decrease in tumour growth in xenograft mouse model." (PMID 34264012, 2021).
tumor (continued). "Notably, at the LUAD tumor stage 3–4 interface, RDM1 was predicted to contribute to LUAD tumor advancement from stage 3 to stage 4." (PMID 34940617, 2021). "The different expression changes of RDM1 across cancers may be related to the different database collection methods and different tumor biological mechanisms." (PMID 34435618, 2021). "We demonstrate that RDM1 acts as a tumor suppressor in HCC by inhibiting cell proliferation." (PMID 31670863, 2020). "Taken together, our study indicates that RDM1 functions as a tumor suppressor and may be a potential prognostic and therapeutic factor for HCC." (PMID 31670863, 2020). "Furthermore, the xenograft mouse model showed stable knockdown of RDM1 significantly inhibits NB tumor growth." (PMID 30868057, 2019). "Furthermore, the tumor size and weight in shRDM1 cells was less than that from the shN cells, confirming the oncogenic role of RDM1 in NB progression." (PMID 30868057, 2019). "Downregulation of RAD52 motif 1 (RDM1), a key regulator of DNA double-strand break repair and recombination, suppresses tumor growth in HCC, whereas deletion of RDM1 promotes HCC cell proliferation." (PMID 37020540, 2023). "Hypermethylation of RDM1 induced by METTL3 suppressed the expression of RDM1, leading to the activation of the Ras/Raf/ERK pathway in tumor progression." (PMID 33879256, 2021). "It was found that the expression of RDM1 was significantly correlated with gender, stage, grade, American Joint Committee on Cancer TNM system-T tumor size (AJCC_T), vascular invasion, alcohol consumption and hepatitis virus status." (PMID 34435618, 2021). "Mechanistically, METTL3 facilitated tumor progression by modulating suppressor of cytokine signaling 2 (SOCS2), RAD52 motif 1 (RDM1) and Snail." (PMID 33879256, 2021). "In the present study, we show that RAD52 motif 1 (RDM1), a key regulator of DNA double‐strand break repair and recombination, is downregulated in HCC tissues and suppresses tumor growth." (PMID 31670863, 2020). "Similarly, there were significant expression differences for RDM1, CDCA3 and FLVCR1 within different tumor stages." (PMID 41048998, 2025). "This study then tested PCNA level in OS and found that inhibition of RDM1 suppressed PCNA expression compared with normal control group, indicating that knockdown of RDM1 inhibited tumour group, which is consistent with the results of tumour volume and tumour weight." (PMID 34264012, 2021). "In 50 pairs of HCC tissues, RDM1 mRNA showed no statistical significance between tumor and nontumor samples." (PMID 31670863, 2020). "In this study, we demonstrated that RDM1 functions as a tumor suppressor in HCC by inhibiting cell proliferation but not migration." (PMID 31670863, 2020). "Finally, the Tumor Immune Assessment Resource (TIMER) and Gene Expression Analysis Interactive Analysis (GEPIA) databases were used to detect the correlation between the expression of RDM1 and expression of marker genes related to immune infiltration." (PMID 34435618, 2021). "In addition, RDM1 expression and LIHC tumor purity (r = 0.221, P=3.29e-05) and the infiltration of B cells (r = 0.30, P=8.19e-09), CD8+ T cells (r = 0.21, P=8.90e-05), macrophages (r = 0.29, P=6.93e-08) and DCs (r = 0.29, P=4.19e-08) showed a significant positive correlation." (PMID 34435618, 2021). "Moreover, RDM1 IHC staining in 57 paired HCC metastatic cases showed no expression differences between primary tumor and portal vein nodules." (PMID 31670863, 2020).
tumor (continued). "We further assessed the predictive value of RDM1 within clinical subgroups, and stratified analysis indicated that low RDM1 levels correlated with poor survival in multiple HCC (P < 0.001), advanced TNM stage (P < 0.001), and large tumor size subgroups (P < 0.001)." (PMID 31670863, 2020). "Unfortunately, we did not detect differential protein expression of RDM1 and RBP4 between normal oral and tumor tissues." (PMID 37647077, 2023).
cancer (10 papers, 2014 to 2024). A tumor composed of atypical neoplastic, often pleomorphic cells that invade other tissues. "Since DNA repair protein RAD52 has previously been implicated in the development of resistance to cancer therapy 22, RDM1 was initially indicated to have a similar function to RAD52 in DNA repair pathways." (PMID 30868057, 2019). "The expression of RDM1 is correlated with the degree of immune infiltration of immune cells, including macrophages and neutrophils, in a variety of cancer types." (PMID 38601075, 2024). "We also revealed that the genes with relatively high expression at 0 h were primarily related to cell growth and proliferation, particularly cancer cell proliferation, such as Tfap4, Rdm1, Ddx39b, Pgam1, and so on." (PMID 36834727, 2023). "Here, we found that high mRNA expression of RDM1 is related to the occurrence and development of cancer." (PMID 34435618, 2021). "Another key finding of the present study was that RDM1 is related to immunity to multiple cancer types." (PMID 34435618, 2021). "The correlation between RDM1 expression and the prognosis of patients with different types of cancer was calculated using the PrognoScan database." (PMID 34435618, 2021). "In recent studies, RDM1 is found to be abnormally expressed in various human cancers, playing a key role in cancer progression." (PMID 34264012, 2021). "At the same time, to expand the sample size, the relationship between RDM1 expression and pan-cancer prognosis was analyzed using the TCGA and GTEx datasets from the GEPIA database." (PMID 34435618, 2021). "Overexpression of RDM1 was observed in several cancers such as the breast cancer and lung adenocarcinoma." (PMID 34046411, 2021). "Subsequently, to fully assess the relationship between RDM1 expression and the prognosis of various cancers, the Kaplan–Meier plotter and PrognoScan databases were used." (PMID 34435618, 2021). "Despite these discoveries, however, to date, little is known about the role of RDM1 in human cancer." (PMID 30069034, 2018). "At the same time, the prognostic value of RDM1 across cancers was well elucidated." (PMID 34435618, 2021). "Decreased expression of RDM1 was noticed to be related to stimulated calcium signaling which contributed to cancer cell survival, together with activated KRAS and RAF pathways which, as upstream of MEK/ERK pathways, enhanced cancer cell growth, survival and metabolism." (PMID 34046411, 2021). "Abnormally, high expression of RDM1 was observed in OS tissues and cancer cells." (PMID 34264012, 2021). "Given the wide‐range biological roles of RDM1, we proposed that RDM1 might constitute an important aspect of cancer initiation and progression." (PMID 31670863, 2020). "Currently, there are few studies examining RDM1 in human cancers." (PMID 31670863, 2020). "Previous studies have revealed that RDM1 promotes cancer growth by inducing G2/M cell cycle arrest." (PMID 31670863, 2020). "Before our study, there were no reports for RDM1 regulation of the RAS–Raf–MEK–ERK signaling pathway during NB cancer progression, and this work also show that RDM1 may be a target for antineoplastic therapies." (PMID 30868057, 2019). "Importantly, RDM1 inhibition is reported to increase the sensitivity of cells to cisplatin, suggesting it may be used as an adjuvant therapy for cancer treatment." (PMID 34264012, 2021). "Particularly, high RDM1 mRNA expression correlated with poor OS and PFS in LIHC patients with stage 1+2, stage 2+3 and stage 3+4 cancer." (PMID 34435618, 2021). "RDM1 expression was also correlated with the degree of immune infiltration of B cells, CD8+ T cells, CD4+ T cells, macrophages, neutrophils and DCs in 16, 9, 12, 17, 12 and 14 cancer types, respectively." (PMID 34435618, 2021).
cancer (continued). "The discovery of fusion transcripts containing partners that regulate repair of DNA double-strand breaks and homologous recombination, such as RAD21, RDM1, BRCA2 and SHFM1, is consistent with abundant evidence for aberrant regulation of DNA replication in cancer." (PMID 24727804, 2014).
RDM1 also shares sentences with these, for which no sentence is quoted: ovarian carcinoma (2 papers); adrenocortical carcinoma (1); astrocytoma (1); bladder cancer (1); brain cancer (1); colon cancer (1); dysplasia (1); gastric cancer (1); glioblastoma (1); large cell carcinoma (1); melanoma (1); non-small cell lung carcinoma (1); prostate carcinoma (1).